SOD1P3 (superoxide dismutase 1 pseudogene 3)
Gene: Processed pseudogene on chromosome 8 (125,951,861 to 125,952,314, reverse strand). Ensembl gene ENSG00000253651.
Diseases named in the same sentence as SOD1P3 in open-access papers:
SOD1P3 is named in the same sentence as 3 diseases in open-access papers, as found by Europe PMC text mining. Sharing a sentence is not in itself a finding about the gene and the disease. The quoted sentences say what the papers report.
lung carcinoma (1 paper, 2024). "SOD3 and SOD1P3 regulate active oxygen in the microenvironment and are downregulated in lung cancer." (PMID 38791918, 2024). "Furthermore, SOD1P3 regulates the processes of angiogenesis, metastasis, and invasion in lung cancer by controlling the levels of Interleukin6 and VEGF." (PMID 38791918, 2024).
cancer (1 paper, 2024). A tumor composed of atypical neoplastic, often pleomorphic cells that invade other tissues. "The gene SOD1P3 (Superoxide Dismutase 1 Pseudogene 3) (average methylation 68%, delta 14%, p = 0.02) substantially influences cancer development." (PMID 38791918, 2024).
tumor (1 paper, 2024). "PD-L1 high-expressing tumors show hypermethylated genes and promoters with strong oncogenic effects (SNORD114-14, DCAF4L2, S100A7L2, and SOD1P3) and hypermethylated genes and promoters with tumor suppressor effects (CELF2-AS1 and LINCMD1)." (PMID 38791918, 2024).